MDM2 (MDM2 proto-oncogene)
Diseases named in the same sentence as MDM2 in open-access papers (continued):
Sharing a sentence is not in itself a finding about the gene and the disease.
bladder cancer (continued). "To further investigate whether hub genes have an impact on the prognosis of bladder cancer, we performed survival analysis of CXCL8, MDM2, TGFB2, FN1, TIMP1, and RPL22L1, and their impact on tumor stage using TCGA database." (PMID 34276798, 2021). "Gene amplification is one of the mechanisms underlying the activation of proto-oncogenes such as ERBB2, CCND1, CCNE1, MDM2, and E2F3, which have been suggested as cancer driver genes in bladder cancers, based on their aberrant gene amplification and protein overexpression." (PMID 27902773, 2016). "CCND1 amplified bladder cancers may be sensitive to CDK4 inhibitors; ERBB2 amplified tumors may be sensitive to lapatinib, trastuzumab, or T-DM1; and MDM2 inhibitors are in current clinical development." (PMID 23593348, 2013). "As the Mdm2 SNP309 was previously shown to be related with disease onset at younger age also in sporadic tumours (eg, bladder cancer) we tested our cases towards this hypothesis." (PMID 18577987, 2008). "Our study elucidated that SNHG1 promotes MDM2 expression by binding to miR-9-3p to promote PPARγ ubiquitination and downregulate PPARγ expression and that SNHG1 plays an important role in bladder cancer and provides a potential therapeutic target for bladder cancer." (PMID 36230661, 2022).
non-small cell lung carcinoma (50 papers, 1997 to 2025). A group of at least three distinct histological types of lung cancer, including non-small cell squamous cell carcinoma, adenocarcinoma, and large cell carcinoma. "This process entails decreased MDM2 level, which upregulates Slug expression, further inhibiting E-cadherin and promoting metastasis in non-small-cell lung cancers." (PMID 41203126, 2025). "Osteocyte small extracellular vesicles (sEVs) miR-99b-3p inhibited the proliferation of non-small cell lung cancer (NSCLC) cells by directly targeting murine double minute 2 (MDM2)." (PMID 38547196, 2024). "MiR-221-3p downregulates the proto-oncogene MDM2, reversing paclitaxel resistance in non-small cell carcinoma and inducing apoptosis." (PMID 36936419, 2023). "Homo-PROTAC 11a induced effective MDM2 dimerization and triggered the proteasomal degradation of MDM2 in A549 non-small cell lung cancer cells." (PMID 36235052, 2022). "It has been shown that Ras mutations repressed H1.4S35p by inducing the degradation of the writer of this PTM, PKA, in an MDM2-dependent way in non-small-cell lung carcinoma (NSCLC) cell lines." (PMID 32824860, 2020). "Low MDM2, high Slug, and low E-cadherin expression correlate with poor prognosis and early metastasis in non-small-cell lung cancer (NSCLC) patients." (PMID 29080116, 2018).
non-small cell lung carcinoma (continued). "Drawing upon the example of non-small cell lung cancer specifically, a comprehensive meta-analysis identified MDM2 SNP309G as a particular female survival risk, but not among all ethnicities." (PMID 33664771, 2021). "Acquired resistance to combined MDM2 and MEK inhibition has been previously observed in colon and non-small cell lung cancer cells." (PMID 35075200, 2022). "Combining MDM2 and PI3K inhibitors in the CAL-51 (breast adenocarcinoma) and NCI-H460 (non-small cell lung cancer) cell lines yielded profound inductions of apoptosis." (PMID 24810962, 2014). "While other studies have also noted MDM2/MDM4 alterations in select HPD patients, this is not the case in non-small cell lung carcinoma (NSCLC)." (PMID 31340855, 2019).
cervical carcinoma (47 papers, 2006 to 2026). A carcinoma arising from either the exocervical squamous epithelium or the endocervical glandular epithelium. "We investigated the association of MDM2 rs2279744 polymorphism and cervical cancer susceptibility in five genetic models." (PMID 36059664, 2022). "In the current meta-analysis, the MDM2 rs2279744 polymorphism showed a significant correlation with cervical cancer in the recessive model (GG vs GT + TT) and homozygote model (GG vs TT)." (PMID 36059664, 2022). "The pooled OR indicated that MDM2 rs2279744 polymorphism in recessive model was closely related to an increased risk of cervical cancer (OR = 1.602, 95% CI: 1.077-2.383, P = 0.020)." (PMID 36059664, 2022). "PIK3CA mutation is associated with poor treatment response and low survival rate, while MDM2 is associated with the development of cervical cancer and poor prognosis." (PMID 35795639, 2022). "Subgroup analysis showed that the association between MDM2 rs2279744 polymorphism and cervical cancer was significant only in population-based studies or high-quality studies." (PMID 36059664, 2022). "In conclusion, this work has provided a novel insight into the interaction between proteasome-associated DUB USP14 and MDM2 in cervical cancer cells." (PMID 33061808, 2020). "MDM2 SNP309 analysis revealed that T allele (71.43%) was more common in cervical cancer patients compared to the control group." (PMID 31350972, 2019). "MDM2 polymorphism analysis revealed that T allele (71.43%) was more common in cervical cancer patients compared to the control group." (PMID 31350972, 2019). "Murine double-minute 2 homolog (MDM2) is another gene that has been studied to be associated with tumorigenesis and poor prognosis in several types of cancer including cervical cancer." (PMID 31350972, 2019). "MDM2 SNP309 analysis revealed that TG genotype has lower association to cervical cancer when compared with the TT and GG genotypes." (PMID 31350972, 2019). "At this stage, there is still no clear association between the presence of PIK3CA mutation and MDM2 polymorphisms and the occurrence of cervical cancer." (PMID 31350972, 2019). "PIK3CA mutation is associated with poor treatment response and low survival rate while MDM2 is associated with tumorigenesis and poor prognosis in cervical cancer." (PMID 31350972, 2019). "We also observed that MDM2 SNP309 T allele was more common that G allele in cervical cancer patients." (PMID 31350972, 2019). "Therefore, definite results for the correlation of MDM2 rs2279744 polymorphism and cervical cancer can be obtained." (PMID 36059664, 2022). "Significant relationship was found between MDM2 rs2279744 polymorphism and cervical cancer." (PMID 36059664, 2022). "The association between MDM2 rs2279744 polymorphism and cervical cancer susceptibility." (PMID 36059664, 2022). "Thus, we determined the prevalence of PIK3CA and MDM2 mutations in Filipino cervical cancer patients." (PMID 31350972, 2019). "PIK3CA and MDM2 SNP309 have been studied to be associated with cervical cancer." (PMID 31350972, 2019). "This is consistent with the results of a single study with a Brazilian population that was carried out to test whether MDM2 SNP309 (rs2278744) was associated with either the risk of cervical cancer or its diagnosis at an early age." (PMID 25075210, 2014).
cervical carcinoma (continued). "However, there have been very few reports on the correlation between SNP of MDM2 gene and cervical cancer susceptibility." (PMID 21660264, 2011). "Four genes associated with survival of cervical cancer patients were selected by survival by univariate analysis: EGFR, TNF-α, VEGFA and MDM2 (P<0.1)." (PMID 40238841, 2025). "It was recently reported that the level of the E3 ubiquitin ligase MDM2 is reduced by IU1 in cervical cancer cells along with the activation of autophagy and proteasome." (PMID 37711852, 2023). "MDM2 SNP309 analysis revealed that TG genotype (p = 0.03; OR 0.18; 95% CI 0.04–0.76) was associated with lower cervical cancer rates than TT genotype." (PMID 35795639, 2022). "Our group previously found other biomarkers of cervical cancer, such as p16, MDM2, galectin-3, H3K9ac and H3K4me3." (PMID 32488496, 2020). "Recent studies have identified E3 ubiquitin ligase MDM2 (Murine double minute 2) as a novel therapeutic target in cervical cancer." (PMID 33061808, 2020). "It has been well established that mdm2 (Murine double minute 2) gene was amplified and/or overexpressed in a variety of human neoplasms, including cervical cancer." (PMID 33061808, 2020). "Recent studies have identified E3 ubiquitin ligase MDM2 as a novel therapeutic target in cervical cancer, unveiling a great treatment opportunity for cervical cancer patients 4, 19-23." (PMID 33061808, 2020). "In this study, we determine the frequency of PIK3CA and MDM2 SNP309 (rs2279744) in Filipino cervical cancer patients." (PMID 31350972, 2019). "Cytochrome P450 is involved in a variety of human metabolic functions, and the genetic polypeptide nature of MDM2 may play a role in the occurrence and development of cervical cancer." (PMID 40238841, 2025). "Furthermore, USP14 selective inhibitor IU1 decreased MDM2 expression, inhibited growth, and triggered apoptosis in cervical cancer cells." (PMID 36999051, 2023).